SCN2A (sodium voltage-gated channel alpha subunit 2)
Description:
Mediates the voltage-dependent sodium ion permeability of excitable membranes. Assuming opened or closed conformations in response to the voltage difference across the membrane, the protein forms a sodium-selective channel through which Na(+) ions may pass in accordance with their electrochemical gradient. Implicated in the regulation of hippocampal replay occurring within sharp wave ripples (SPW-R) important for memory (By similarity).
Synonyms: HBA; NAC2; SCN2A1; SCN2A2; Nav1.2; HBSCII; HBSCI; BFIC3; BFIS3; BFNIS; DEE11; EA9; EIEE11; Na(v)1.2
Tractability: Small molecule: an approved drug acts on it; a structure with a bound ligand is known; a high-quality ligand is known; it belongs to a druggable protein family. Antibody: UniProt places it where antibodies can reach, with high confidence; its Gene Ontology location is reachable by antibodies, with high confidence; UniProt predicts a signal peptide or a membrane-spanning region. PROTAC: UniProt records ubiquitination sites on it; ubiquitination databases record sites on it; a small molecule that binds it is known.
Target class: Voltage-gated ion channel; Voltage-gated sodium channel; Ion channel
Chemical probes: BIII 890CL  (high quality)
Gene: Protein-coding gene on chromosome 2 (165,194,993 to 165,392,310, forward strand). Ensembl gene ENSG00000136531.
Subcellular location: Cell membrane
Pathways (Reactome):
Developmental Biology: Interaction between L1 and Ankyrins
Muscle contraction: Phase 0 - rapid depolarisation
Sensory Perception: Sensory perception of sweet, bitter, and umami (glutamate) taste
Gene Ontology:
Molecular function: calmodulin binding; protein binding; voltage-gated sodium channel activity; monoatomic cation channel activity; monoatomic ion channel activity
Biological process: neuronal action potential; cardiac muscle cell action potential involved in contraction; cellular response to hypoxia; intrinsic apoptotic signaling pathway in response to osmotic stress; memory; myelination; nervous system development; neuron apoptotic process; sodium ion transmembrane transport; sodium ion transport; action potential; monoatomic ion transport; transmembrane transport
Cellular component: plasma membrane; axon; membrane; node of Ranvier; voltage-gated sodium channel complex
Genetic constraint (gnomAD): Loss-of-function variants: 18 observed, 165.81 expected, observed/expected ratio (o/e) 0.11, 90% interval 0.074 to 0.16. The upper end of that interval is the gene's LOEUF score, 0.16, which puts it in group 1 of 6, group 1 being the genes least tolerant of losing a copy. Missense variants: 1,179 observed, 2,333.3 expected, observed/expected ratio (o/e) 0.51, 90% interval 0.48 to 0.53. Synonymous variants: 753 observed, 809.15 expected, observed/expected ratio (o/e) 0.93, 90% interval 0.88 to 0.99.
Gene-disease validity (ClinGen):
ClinGen rates the evidence that SCN2A causes each of these diseases.
complex neurodevelopmental disorder (autosomal dominant): Definitive. A disorder that involves more than one phenotype associated with the central nervous system, including but not limited to intellectual disability, autism, and seizures (epilepsy).
Homologues: Orthologues: chimpanzee SCN2A (99% identical), macaque SCN2A (99% identical), rabbit SCN2A (99% identical), dog SCN2A (99% identical), pig SCN2A (99% identical), mouse Scn2a (98% identical), rat Scn2a (98% identical), guinea pig SCN2A (96% identical). Paralogues in human: SCN1A (88% identical), SCN3A (87% identical), SCN9A (77% identical), SCN8A (76% identical), SCN4A (65% identical), SCN5A (64% identical), SCN10A (57% identical), SCN11A (47% identical), SCN7A (45% identical), CACNA1A (25% identical), CACNA1B (24% identical), CACNA1D (24% identical), and 14 more.
Diseases named in the same sentence as SCN2A in open-access papers:
SCN2A is named in the same sentence as 152 diseases in open-access papers, as found by Europe PMC text mining. Sharing a sentence is not in itself a finding about the gene and the disease. The quoted sentences say what the papers report.
epilepsy (221 papers, 2009 to 2026). A brain disorder characterized by episodes of abnormally increased neuronal discharge resulting in transient episodes of sensory or motor neurological dysfunction, or psychic dysfunction. "Studies have established the therapeutic potential of SCN2A as a pharmacological target in mitigating the severity of diseases associated with dysfunction of the Nav1.2 channel, such as epilepsy, seizures, and ASD/ID." (PMID 40507552, 2025). "Mutation of the SCN2A gene has been confirmed to cause epilepsy, dyskinesia, autism spectrum disease, intellectual disorders, paroxysmal ataxia, paroxysmal hemiplegia and other neurological diseases." (PMID 40236662, 2025). "SCN2A variants associated with neonatal and early infantile epilepsies generally produce increased Nav1 activity (GOF) and typically respond well to SCBs." (PMID 41515912, 2025). "Group 2—Intermediate epilepsy/metabolic disorders (Ion-channel and neuronal-excitability phenotype): This group comprised patients harboring variants in SCN2A, PAH, IQSEC2, and GNPAT." (PMID 41300846, 2025). "The phenotypic data reveal consistent trends in SCN2A-associated conditions, including a high prevalence of seizures, epilepsy, psychiatric and behavioral features, physical abnormalities, and developmental delays." (PMID 40507552, 2025). "Pathogenic mutations in SCN2A have been associated with a spectrum of epilepsies and neurodevelopmental disorders." (PMID 40894881, 2025). "Previous studies have extensively documented the association between SCN2A mutations and epilepsy, particularly in early-onset cases." (PMID 40507552, 2025). "For example, SCN2A variants produced a broad clinical spectrum ranging from epilepsy to severe neurodevelopmental disorders, reflecting variable expressivity and genotype-specific functional effects." (PMID 41300846, 2025). "While several rodent models (e.g., Scn1a, Scn2a, and Gabrb3 mutants) represent specific genetic mutations associated with epilepsy, others such as GAERS or WAG/Rij rats display spontaneous spike–wave discharges typical of GGEs." (PMID 41585885, 2025). "SCN2A variants with GoF properties are closely associated with unprovoked seizures and epilepsy, whereas those with LoF effects (missense and protein-truncating variants) are typically associated with ASD and ID." (PMID 41151066, 2025). "This investigation aims to delve into the influence of SCN1A and SCN2A gene polymorphisms on the effectiveness of VPA in managing epilepsy among the Han Chinese population." (PMID 38837984, 2024). "GoF pathogenic variants in SCN2A often lead to early infantile DEEs, whereas loss‐of‐function (LoF) generally causes later‐onset epilepsy with a moderate impact on executive functions or autism spectrum disorder (ASD) without epilepsy." (PMID 39526481, 2024). "A milder form of epilepsy is linked to Scn2a mutations, typically presenting with focal seizures in infancy and a better prognosis." (PMID 39452036, 2024). "Regarding the etiology of epilepsy, five (11.1%) were genetic, including one with SCN2A mutation, one with KCNA2 mutation, one with MBD5 mutation, one with WFS1 mutation, and one with OCRL mutation." (PMID 38419715, 2024). "Regardless, the hyperexcitability of some neuron types in response to Nav1.2 loss/reduction is likely contributing to the seizure disorders experienced by individuals with LOF SCN2A mutations." (PMID 39606727, 2024). "Currently, it is thought that SCN2A-related disorders bifurcate into two categories: neurodevelopmental disorders caused by LOF or seizure disorders caused by GOF in Nav1.2." (PMID 39606727, 2024). "Significantly, the Nav1.2/Nav1.6 channels are encoded by epilepsy-associated ion channel genes SCN2A and SCN8A." (PMID 38091244, 2024).
epilepsy (continued). "Several studies have shown that most epilepsy-related missense variants identified in SCN2A usually occur de novo as in the case of family 1, which enhances the pathogenicity of the variant." (PMID 38255008, 2024). "In SCN2A variant patients, anticonvulsants were effective in 85.7% (12 of 14) of patients, epilepsy was controlled in 57.1% (8 of 14), and the seizure frequency decreased in 16.3% (4 of 14)." (PMID 38174099, 2023). "We previously proposed that impaired CS excitatory neurotransmission causes epilepsies in Scn2a haplo-deficient mouse." (PMID 37219072, 2023). "On the contrary, late-onset forms of epilepsy are associated with LoF truncation mutations in the SCN2A gene." (PMID 38003469, 2023). "Regarding the first group, many of the gene changes have been previously associated with epilepsy, such as the SCN2A gene (AUT108 and AUT187)." (PMID 38003033, 2023). "An estimated 20–30% of children with loss-of-function SCN2A variants develop epilepsy, often after the first year of life." (PMID 38151324, 2023). "Mutations in SCN2A are associated with a spectrum of neurological disorders from benign to severe epilepsies, autism spectrum disorder and intellectual disability." (PMID 37008993, 2023). "In total, six of the 14 patients with SCN2A variant epilepsy had early onset EE, of whom four received sodium channel blockers, seizures were controlled in 1 patient after OXC addition, and seizures decreased in one patient after OXC addition." (PMID 38174099, 2023). "Studies have shown that many patients with epilepsy-related SCN2A mutations present with complex GoF or LoF characteristics, and some rare mutations share both characteristics." (PMID 38174099, 2023). "Sodium channel inhibitors, such as carbamazepine, phenytoin, oxcarbazepine, lamotrigine and TPM, are generally expected to be effective in treating epilepsy patients who have a mutation in SCN2A (Nav1.2)." (PMID 40217485, 2023). "On the contrary, seizures occurring during the course of late-onset forms of epilepsy, which are associated with LoF truncation SCN2A mutations, worsened during treatment with sodium channel inhibitors." (PMID 38003469, 2023). "SCN1A/SCN2A/SCN8A variant-related epilepsy was generally manifested at an earlier age, while the SCN3A/SCN9A/SCN1B variant-related subtype showed a later age at onset." (PMID 38174099, 2023). "Generally, mutations altering neuronal sodium channel structure, function, or expression lead to epilepsy and neurological disease, and SCN2A stop codon mutations lead to termination of protein translation in autism." (PMID 36768153, 2023). "Previous models suggest that SCN2A variants that cause an enhancement of neuronal excitability result in epilepsy and are gain-of-function, whereas, ASD-linked variants are loss-of-function and reduce channel activity." (PMID 38293651, 2023). "Of 14 SCN2A variant patients, two were diagnosed with OS, one with West syndrome, one had epilepsy of infancy with migrating focal seizures (EIMFS), two had benign familial epilepsy, and eight had non-specific EE." (PMID 38174099, 2023). "Unexpectedly, we identified Nav1.2 (encoded by Scn2a), a key ion channel implicated in epilepsy and neuronal excitability among the highest-ranked mTORC2-regulated phosphorylated proteins." (PMID 37963879, 2023). "Neurological conditions like epilepsy, autism spectrum disorders, intellectual disability, and schizophrenia have been linked to mutations of the Scn2a gene, which codes for the voltage-gated sodium channel alpha-II subunit Nav1.2." (PMID 36979479, 2023). "Recent studies have reported similar hyperexcitable neurons that carry ASD- and epilepsy-related mutations for SCN2A (Sodium channel protein type 2 subunit alpha)." (PMID 36083912, 2022). "In this study, epilepsy patients with SCN2A variants from 2 pediatric clinical centers in China were studied." (PMID 35431799, 2022).
epilepsy (continued). "In this study, we have found 59 SCN2A variants in 72 Chinese epilepsy patients, and 22 of them are novel variants." (PMID 35431799, 2022). "Some of the patients in this study were diagnosed with epilepsy at our clinical center at an early stage of life and were confirmed with SCN2A variants in recent years." (PMID 35431799, 2022). "Recently, SCN2A mutations have been implicated with epilepsy of infancy with migrating focal seizures (EIMFS) syndrome, benign familial neonatal infantile seizures (BFNIS) and early infantile epileptic encephalo-pathy (EIEE)." (PMID 35801810, 2022). "The common epilepsy phenotypes of patients with SCN2A variants include benign epilepsy in the first year of life, Ohtahara syndrome, West syndrome, and EIEE." (PMID 35431799, 2022). "In these disorders and epilepsies, carriers of whole-gene deletions are less severely affected than carriers of single point mutations (e. g., in SCN2A, KCNT1, KCNA2, SPTAN1)." (PMID 38835873, 2022). "Some studies have found that a correlation between age at disease onset, response to sodium channel blockers and the functional properties of mutations in children with SCN2A-related epilepsy." (PMID 35715422, 2022). "In this study, the association of sodium channel genes SCN1A and SCN2A polymorphisms with drug-resistant epilepsy was studied." (PMID 35136380, 2022). "Variations in SCN2A gene are associated with a spectrum of neurodevelopmental and epileptic disorders, such as epilepsy, intellectual disability, ASD, schizophrenia, and periodic ataxia, presenting an autosomal dominant inheritance." (PMID 35431799, 2022). "The sodium channel genes SCN1A and SCN2A encode the α subunit of voltage-gated sodium channels, and thus, mutations in these genes can be potential source of drug resistance in epilepsy." (PMID 35136380, 2022). "This case-control (100 control: 101patients) study evaluated the association of sodium channel genes SCN1A and SCN2A with drug-resistant epilepsy." (PMID 35136380, 2022). "We propose that the rs2169312, rs13405797, rs2162600 of SCN1A and rs353139 of SCN2A are risk factor for epilepsy among individual with history of febrile seizure." (PMID 35801810, 2022). "In this study, the phenotypic spectrum, treatment, and prognosis of epilepsy children with SCN2A variants were studied in a Chinese cohort from two pediatric clinical centers." (PMID 35431799, 2022). "Variants in SCN1A and SCN2A have been linked to a spectrum of epilepsy phenotypes, including DS, generalised epilepsy with febrile seizures plus (GEFS+), WS and some other infantile epileptic disorders." (PMID 34163418, 2021). "Further studies are required to identify and characterize more SCN2A mutations and their involvements in epilepsies." (PMID 33841294, 2021). ": This meta-analysis will summarize the effects of SCN1A and SCN2A gene polymorphisms on VPA response in children with epilepsy." (PMID 34011048, 2021). "This work investigated how two ion channel mutations, one associated with autism (Scn2a‐null) and one with epilepsy (Kcna1‐null), interact to modify genotype–phenotype relationships in the context of autism." (PMID 33484493, 2021). "Variants in SCN2A have also been linked to several other neurological disorders, including epilepsy and intellectual disability." (PMID 34156984, 2021). "This work investigates how two ion channel mutations, one associated with autism (Scn2a‐null) and one with epilepsy (Kcna1‐null), interact to modify genotype–phenotype relationships in the context of autism." (PMID 33484493, 2021). "In this study, a meta-analysis was used to further explore the effects of SCN1A and SCN2A gene polymorphism on VPA response in children with epilepsy." (PMID 34011048, 2021). "Advanced search was done using the following keyword combinations: SCN1A mutations in epilepsy, SCN1B mutations in epilepsy, SCN2A mutations in epilepsy, SCN3A mutations in epilepsy, SCN8A mutations in epilepsy and functional studies of VGSCs in epilepsy." (PMID 33841294, 2021).
epilepsy (continued). "Similar to the KCNQ2 variants, GoF SCN2A variants can also cause a spectrum of intractable childhood epilepsies ranging from Ohtahara syndrome and migrating focal seizures to epileptic spasms and Dravet syndrome." (PMID 34356067, 2021). "SCN1A, SCN2A, SCN3A, and SCN8A genes which individually encode voltage-gated sodium channels, that is NaV1.1, NaV1.2, NaV1.3, and NaV1.6, are related to early onset epilepsies." (PMID 34276290, 2021). "It is little wonder, then, that mutations in SCN2A lead to intellectual disability, epilepsy, and autism." (PMID 32264956, 2020). "We did not identify pathogenic variants in the cardiac‐expressed SCN5A gene in our cohort or in the epilepsy‐associated genes SCN2A and SCN8A." (PMID 32449611, 2020). "Enhancements of Nav1.2-mediated persistent currents have been identified as resulting from six of 23 SCN2A epilepsy mutations that have been studied in vitro." (PMID 32244818, 2020). "Further to this, independent GWAS studies that show multiple significant associations between SNPs associated with SCN1A/SCN2A and epilepsy and/or febrile seizures, fail to do so for SCN9A." (PMID 33216760, 2020). "Several SCN2A epilepsy mutations have also been shown to increase persistent currents through Nav1.2." (PMID 32244818, 2020). "Two of these mutations, A263V and R1882Q, are among the most frequently reported epilepsy mutations in the SCN2A gene and are implicated in epilepsy cases that are refractory to conventional antiepileptic drugs." (PMID 32244818, 2020). "The enhancement of Nav1.2-mediated persistent and resurgent currents by some SCN2A epilepsy mutations is predicted to play a role in epileptogenesis." (PMID 32244818, 2020). "Many of these refractory epilepsies are believed to be manifestations of mutations in SCN2A, the gene for the human voltage-gated sodium channel hNav1.2." (PMID 32244818, 2020). "Normally, LoF SCN2A gene mutations for epilepsy are related to late-onset epilepsy; however, the mechanism of action is unclear." (PMID 33013363, 2020). "Over 150 mutations in the SCN2A gene, which encodes the neuronal Nav1.2 protein, have been implicated in human epilepsy cases." (PMID 31558572, 2019). "Although over 150 different mutations in the Nav1.2 gene, SCN2A, have been reported as likely causes of epilepsy, biophysical characterization of only about two dozen of these mutations have been reported to date." (PMID 31558572, 2019). "Although loss of Nav1.2 function is common among late-onset SCN2A epilepsies, the choreoathetosis associated with the R853Q mutation suggests an underlying neuronal hyperexcitability." (PMID 31558572, 2019). "Nav1.2, a voltage-gated sodium channel subunit encoded by the Scn2a gene, has been implicated in various brain disorders, including epilepsy, autism spectrum disorder, intellectual disability, and schizophrenia." (PMID 31249508, 2019). "SCN2A mutations that lead to a gain of Nav1.2 function are thought to induce early onset epilepsy, whereas those that lead to a loss of Nav1.2 function induce ASD and intellectual disability." (PMID 31249508, 2019). "Mutations of the SCN2A gene encoding a voltage-gated sodium channel alpha-II subunit Nav1.2 are associated with neurological disorders such as epilepsy, autism spectrum disorders, intellectual disability, and schizophrenia." (PMID 30962870, 2019). "Over 150 mutations in the SCN2A gene, which encodes the neuronal voltage-gated sodium channel Nav1.2, have been implicated in human epilepsy cases, but few of them have been studied in vitro to determine the molecular basis of their pathogenicity." (PMID 31558572, 2019). "This pathomechanism was also observed in hippocampal pyramidal neurons of a Q54 transgenic mouse model carrying a gain-of-function Scn2a variant and showing a progressive epilepsy phenotype." (PMID 30813884, 2019).